NINJ1 (ninjurin 1)
Description:
[Ninjurin-1]: Effector of various programmed cell death, such as pyroptosis and necroptosis, which mediates plasma membrane rupture (cytolysis). Oligomerizes in response to death stimuli and forms ring-like structures on the plasma membrane: acts by cutting and shedding membrane disks, like a cookie cutter, leading to membrane damage and loss that cannot be repaired by the cell. Plasma membrane rupture leads to release intracellular molecules named damage-associated molecular patterns (DAMPs) that propagate the inflammatory response. Mechanistically, mediates plasma membrane rupture by introducing hydrophilic faces of 2 alpha helices into the hydrophobic membrane. Induces plasma membrane rupture downstream of Gasdermin (GSDMA, GSDMB, GSDMC, GSDMD, or GSDME) or MLKL during pyroptosis or necroptosis, respectively. Acts as an effector of PANoptosis downstream of CASP1, CASP4, CASP8 and RIPK3 (By similarity). Also induces plasma membrane rupture in response to cell swelling caused by osmotic stress and ferroptosis downstream of lipid peroxidation (By similarity). Acts as a regulator of Toll-like receptor 4 (TLR4) signaling triggered by lipopolysaccharide (LPS) during systemic inflammation; directly binds LPS. Involved in leukocyte migration during inflammation by promoting transendothelial migration of macrophages via homotypic binding (By similarity). Promotes the migration of monocytes across the brain endothelium to central nervous system inflammatory lesions. Also acts as a homophilic transmembrane adhesion molecule involved in various processes such as axonal growth, cell chemotaxis and angiogenesis. Promotes cell adhesion by mediating homophilic interactions via its extracellular N-terminal adhesion motif (N-NAM). Involved in the progression of the inflammatory stress by promoting cell-to-cell interactions between immune cells and endothelial cells. Plays a role in nerve regeneration by promoting maturation of Schwann cells. Acts as a regulator of angiogenesis. Promotes the formation of new vessels by mediating the interaction between capillary pericyte cells and endothelial cells (By similarity). Promotes osteoclasts development by enhancing the survival of prefusion osteoclasts (By similarity). Also involved in striated muscle growth and differentiation (By similarity). [Secreted ninjurin-1]: Secreted form generated by cleavage, which has chemotactic activity (By similarity). Acts as an anti-inflammatory mediator by promoting monocyte recruitment, thereby ameliorating atherosclerosis.
Synonyms: hNINJ1; NIN1; NINJURIN
Tractability: Small molecule: a structure with a bound ligand is known. Antibody: UniProt places it where antibodies can reach, with high confidence; its Gene Ontology location is reachable by antibodies, with high confidence; UniProt predicts a signal peptide or a membrane-spanning region. PROTAC: ubiquitination databases record sites on it; its protein half-life has been measured.
Gene: Protein-coding gene on chromosome 9 (93,121,496 to 93,134,310, reverse strand). Ensembl gene ENSG00000131669.
Subcellular location: Cell membrane (Ninjurin-1); Synaptic cell membrane; Secreted (Secreted ninjurin-1)
Gene Ontology:
Molecular function: cell adhesion mediator activity; lipopolysaccharide binding; membrane destabilizing activity; protein binding; cell-cell adhesion mediator activity
Biological process: cell adhesion; cytolysis; leukocyte chemotaxis involved in inflammatory response; positive regulation of angiogenesis; positive regulation of inflammatory response; programmed necrotic cell death; protein homooligomerization; pyroptotic cell death; cellular hyperosmotic response; ferroptosis; heterotypic cell-cell adhesion; muscle cell differentiation; nervous system development; positive regulation of toll-like receptor 4 signaling pathway; tissue regeneration
Cellular component: plasma membrane; synaptic membrane; extracellular region; membrane
Genetic constraint (gnomAD): Loss-of-function variants: 6 observed, 10.73 expected, observed/expected ratio (o/e) 0.56, 90% interval 0.31 to 1.1. The upper end of that interval is the gene's LOEUF score, 1.1, which puts it in group 4 of 6, group 1 being the genes least tolerant of losing a copy. Missense variants: 170 observed, 208.08 expected, observed/expected ratio (o/e) 0.82, 90% interval 0.72 to 0.93. Synonymous variants: 100 observed, 93.89 expected, observed/expected ratio (o/e) 1.07, 90% interval 0.9 to 1.26.
Homologues: Orthologues: macaque NINJ1 (98% identical), chimpanzee NINJ1 (94% identical), mouse Ninj1 (88% identical), rat Ninj1 (88% identical), guinea pig NINJ1 (86% identical), dog NINJ1 (84% identical), pig NINJ1 (84% identical), rabbit NINJ1 (82% identical), tropical clawed frog ninj1 (63% identical), zebrafish ninj1 (58% identical). Paralogues in human: NINJ2 (49% identical).
Diseases named in the same sentence as NINJ1 in open-access papers:
NINJ1 is named in the same sentence as 102 diseases in open-access papers, as found by Europe PMC text mining. Sharing a sentence is not in itself a finding about the gene and the disease. The quoted sentences say what the papers report.
atherosclerosis (10 papers, 2021 to 2026). A disease characterized by the build-up of fatty material and calcium deposition in the arterial wall resulting in partial or complete occlusion of the arterial lumen. "While Ninjurin-1 (Ninj1) has been implicated in inflammatory diseases, its endothelial-specific role in atherosclerosis remains unclear." (PMID 41280941, 2025). "NINJ1 exerts cell-type-specific functions in endothelial cells, macrophages, smooth muscle cells and pericytes, contributing to atherosclerosis, myocardial infarction, aortic aneurysm and ischemia-reperfusion injury." (PMID 41841425, 2026). "Our results provide the first evidence that endothelial Ninj1 functions as a novel activator of the NF-κB/CXCL-8 axis, establishing its causal role in atherosclerosis and highlighting its potential as a targeted anti-inflammatory therapy." (PMID 41280941, 2025). "In this study, we investigated the endothelial-specific role of Ninj1 in atherosclerosis through complementary in vitro and in vivo approaches, and further elucidated the molecular and signaling mechanisms underlying its effects." (PMID 41280941, 2025). "NINJ1 promotes the adhesion of inflammatory cells to endothelial cells and their transendothelial migration to the sites of atherosclerosis, thereby facilitating the progression of atherosclerosis." (PMID 40356625, 2025). "To investigate Ninj1’s role in atherosclerosis, we synthesized mPN12, a competitive inhibitory peptide targeting Ninj1’s adhesion domain (Pro26-Asn37) and evaluated its effects on plaque development in ApoE−/− mice." (PMID 41280941, 2025). "This study provides the first comprehensive evidence that endothelial Ninj1 promotes atherosclerosis by activating the NF-κB/CXCL-8 signaling axis." (PMID 41280941, 2025). "Collectively, our in vivo and in vitro findings reveal a previously underappreciated endothelial-specific mechanism by which Ninj1 contributes to atherosclerosis." (PMID 41280941, 2025). "In summary, our study establishes a novel endothelial-specific mechanism by which Ninj1 drives atherosclerosis through CXCL-8-mediated NF-κB activation." (PMID 41280941, 2025). "Given endothelial dysfunction’s pivotal role as both the initiator and perpetuator of atherosclerosis, resolving this paradox is essential for understanding Ninj1’s potential involvement in vascular inflammation and atherosclerosis." (PMID 41280941, 2025). "KEGG pathway analysis confirmed significant enrichment of these core genes in NF-κB signaling, suggesting Ninj1 regulates endothelial inflammation through this pathway in atherosclerosis." (PMID 41280941, 2025). "First, endothelial-specific Ninj1 knockout models are required to delineate its in vivo contribution to atherosclerosis." (PMID 41280941, 2025). "We conducted integrated molecular, functional, and histological analyses to characterize Ninj1 expression and function in atherosclerosis." (PMID 41280941, 2025). "Accumulating data demonstrate that Ninj-1 plays important roles in the development of various pathologies including inflammatory processes, diabetes, atherosclerosis, stroke, cancer, or erectile dysfunction." (PMID 37189375, 2023). "Some studies reported that Ninj1 is upregulated in many inflammatory diseases, such as multiple sclerosis, rheumatoid arthritis, pulmonary fibrosis, and atherosclerosis." (PMID 35392805, 2022). "Ninjurin1 (Ninj1), an adhesion molecule, regulates macrophage function in hyaloid regression, multiple sclerosis, and atherosclerosis." (PMID 34974535, 2022). "Given the critical role of endothelial dysfunction in atherosclerosis initiation, we examined whether Ninj1 silencing protects endothelial cells from ox-LDL-induced damage." (PMID 41280941, 2025). "NINJ1 and MMP9 are closely associated with the occurrence and progression of atherosclerosis." (PMID 40356625, 2025).
atherosclerosis (continued). "NINJ1 plays an important role in atherosclerosis, with existing studies showing that NINJ1 expression is elevated in various inflammatory cells involved in atherosclerosis." (PMID 40356625, 2025). "In this context, elucidating the role of NINJ1 in inflammation and plaque progression could provide valuable insights into the development of atherosclerosis." (PMID 40264785, 2025). "To elucidate the molecular mechanisms by which Ninj1 promotes atherosclerosis, we performed transcriptomic sequencing of Ninj1-silenced HUVECs, identifying 430 differentially expressed genes (DEGs; |log2FC| >1, FDR <0.05), including 350 upregulated and 80 downregulated genes." (PMID 41280941, 2025). "We propose that Ninj-1 plays a regulatory role between inflammation and transendothelial transport, making this protein an attractive therapeutic target for the alleviation of the processes involved in diabetes accelerated atherosclerosis." (PMID 37189375, 2023). "Ninj1 mediates cell–cell communication in pulmonary fibrosis, MS, and atherosclerosis." (PMID 34974535, 2022). "Owing to the adhesion activity of NINJ1, NINJ1 enhances the adhesion between immune cells and vascular endothelial cells, thereby playing a key role in nervous system inflammation and peripheral inflammatory diseases like pulmonary fibrosis and atherosclerosis." (PMID 39958360, 2025). "Given the critical role of Ninjurin-1 (NINJ1) in plasma membrane rupture, its involvement in macrophage cell death during atherosclerosis deserves further investigation, as impaired clearance of dead cell corpses contributes to disease progression." (PMID 40264785, 2025).
Sepsis (10 papers, 2020 to 2026). Sepsis is defined as life-threatening organ dysfunction caused by a dysregulated host response to infection. "In sepsis, where excessive and uncontrolled inflammation underlies tissue injury and lethality, NINJ1 represents a novel and promising therapeutic target for attenuating inflammatory damage without interfering with the initial pathogen-sensing or cell death machinery." (PMID 40558557, 2025). "Markers of lipid peroxidation, such as oxidized phospholipids, and NINJ1 expression are elevated in patients with sepsis and inflammatory conditions." (PMID 41518848, 2026). "This positions Fer-1 and other inhibitors of the lipid peroxidation-NINJ1-DAMP axis as promising therapeutics for sepsis-induced ALI." (PMID 41518848, 2026). "During severe infections such as sepsis and COVID-19, NINJ1 regulates the activation and PMR of platelets and the release of procoagulant microvesicles to promote the formation of thrombosis and disseminated intravascular coagulation." (PMID 39958360, 2025). "Inhibiting NINJ1 through haploinsufficiency or glycine treatment reduces cytokine release and protects against sepsis-induced coagulopathy." (PMID 40075648, 2025). "Inhibiting NINJ1-dependent PMR protects against LPS-induced sepsis and inflammasome-induced blood coagulation and inflammation, as well as platelet activation and PANoptosis in septic disseminated intravascular coagulation." (PMID 39958360, 2025). "We used a cecal perforation model that was more consistent with the clinical characteristics of sepsis to assess the role of NINJ1." (PMID 36835580, 2023). "Cecal perforation-induced sepsis and FeCl3-induced thrombosis models were used to evaluate the role of NINJ1 in platelet, thrombus and DIC in vivo." (PMID 36835580, 2023). "Next, cecal ligation and puncture (CLP) was used to establish a sepsis mouse model, and the role of NINJ1 in sepsis was investigated by tail vein injection of NINJ126–37." (PMID 36835580, 2023). "Overall, we have identified the critical role of NINJ1 in platelet activation and thrombosis in sepsis, and that this role is closely related to NINJ1-mediated platelet plasma membrane disruption." (PMID 36835580, 2023). "The liver is known to express high levels of Ninj1,3 and it has been reported that the hepatic expression of Ninj1 is enhanced during sepsis‐induced systemic inflammation." (PMID 36071453, 2022). "Our results indicate that inhibition of NINJ1 significantly delayed the progression of DIC in sepsis, which may provide new ideas for anti-platelet and anti-thrombotic therapy in patients with sepsis." (PMID 36835580, 2023). "And research demonstrates that Nerve injury-induced protein 1 (NINJ1) modulates thrombus formation and disseminated intravascular coagulation (DIC) in sepsis through regulating panoptosis and platelet activation." (PMID 40832104, 2025). "Importantly, NINJ1-targeted interventions—including monoclonal antibodies (e.g., Clone D1), blocking peptides, and small-molecule inhibitors such as glycine and muscimol—have shown efficacy in reducing inflammation and organ injury in experimental models of sepsis." (PMID 40558557, 2025). "It is not clear what mechanisms control NINJ1 regulation in this context but understanding this may provide opportunities to control damaging NINJ1-mediate cell lysis driven pathology associated with over-inflammation such as sepsis." (PMID 37266429, 2023). "The results also reveal that inhibition of NINJ1 suppresses platelet PANoptosis and delays the progression of DIC in sepsis." (PMID 36835580, 2023). "We found that inhibition of NINJ1 effectively alleviated platelet activation and PANoptosis, thereby preventing thrombosis and progression of DIC in sepsis." (PMID 36835580, 2023). "Our study, for the first time, reveals the potential of NINJ1 as a therapeutic target for thrombosis and DIC in sepsis." (PMID 36835580, 2023).
Sepsis (continued). "NINJ1 facilitates immune cell migration to sites of inflammation and promotes inflammation through Toll-like receptor 4 (TLR4) signaling activation, as demonstrated in a sepsis mouse model." (PMID 40075648, 2025). "The results show that inhibition of NINJ1 could significantly reduce the activation of platelets and the formation of DIC in sepsis, thereby improving the survival rate of septic mice." (PMID 36835580, 2023). "In vivo studies demonstrate that inhibition of NINJ1 effectively reduces platelet activation and membrane disruption, thus suppressing platelet-cascade reaction and leading to anti-thrombosis and anti-DIC in sepsis." (PMID 36835580, 2023). "In a LPS-induced sepsis mouse model, Ninj1−/− mice showed similar survival to WT mice, whereas Casp11−/− mice showed a significantly improved survival, indicating that GSDMD activation without NINJ1 control leads to cell death." (PMID 37664463, 2023).
pulmonary fibrosis (9 papers, 2018 to 2025). Chronic progressive interstitial lung disorder characterized by the replacement of the lung tissue by connective tissue, leading to progressive dyspnea, respiratory failure, or right heart failure. "We demonstrated that Ninj1 deficiency ameliorated the bleomycin (BLM)-induced pulmonary fibrosis, which is the most commonly used pulmonary fibrosis model." (PMID 30510259, 2018). "Whether NINJ1-dependent PMR exacerbates tissue damage in disease is unclear, but Ninj1 deficiency is reported to attenuate mouse models of pulmonary fibrosis and multiple sclerosis." (PMID 37196676, 2023). "Ninj1 also plays a crucial role in pulmonary fibrosis by promoting the interactions between macrophages and alveolar epithelial cells." (PMID 38255907, 2024). "Nerve injury-induced protein 1 (Ninjurin1, Ninj1) is an adhesion molecule involved in the pathogenesis of inflammatory disease and pulmonary fibrosis." (PMID 35392805, 2022). "During development of colitis and lung fibrosis, the Ninj1 pathway controlled activation of the macrophages, resulting in the triggering an inflammatory response." (PMID 31963519, 2020). "Upon bleomycin treatment, Ninj1 KO mice ameliorated lung fibrosis; however, the number of infiltrating macrophages from both KO and WT mice were not different." (PMID 31963519, 2020). "In order to determine if Ninj1 plays a role in developing pulmonary fibrosis, we first examined the expression of Ninj1 in the lung specimens from normal people (n = 8) and IPF patients (n = 29)." (PMID 30510259, 2018). "We found that the expression of Ninj1 in a patient cohort was upregulated in the lung specimens of idiopathic pulmonary fibrosis patients as well as mice with bleomycin-induced pulmonary fibrosis." (PMID 30510259, 2018). "Ninj1 could stimulate the inflammatory response of macrophages and thus promote the development of pulmonary fibrosis." (PMID 37858098, 2023). "A cohort study of idiopathic pulmonary fibrosis patients revealed that Ninj1 expression was increased in fibrosis patients compared to that in normal patients; this pattern was also observed in a mouse IPF model, in which Ninj1 mediated alveolar epithelial cell and macrophage interaction." (PMID 34974535, 2022). "To summarize our results, we have investigated a novel function of Ninj1 in pulmonary fibrosis." (PMID 30510259, 2018). "In this study, we hypothesized that Ninj1 could play a crucial role in developing pulmonary fibrosis, which is a chronic inflammatory disease." (PMID 30510259, 2018). "This study revealed the involvement of Ninj1 in stimulation of inflammatory response in macrophages by promoting contact-dependent interaction with AECs, thereby proving a contribution in developing pulmonary fibrosis." (PMID 30510259, 2018). "Interestingly, as pulmonary fibrosis was induced, the expression levels of Ninj1 mRNA and protein were markedly elevated after BLM injection." (PMID 30510259, 2018). "In this study, we aimed to investigate a novel function of Ninj1 in pulmonary fibrosis." (PMID 30510259, 2018). "We also investigated Ninj1 expression level in BLM-induced pulmonary fibrosis model." (PMID 30510259, 2018). "Here, we further demonstrated a novel role of Ninj1 during the development of pulmonary fibrosis." (PMID 30510259, 2018). "Therefore, hypothesizing that Ninj1 may contribute to the development of pulmonary fibrosis, we compared the development of pulmonary fibrosis between WT and Ninj1 KO mice." (PMID 30510259, 2018). "Consequently, Ninj1 may be involved in the development of pulmonary fibrosis by enhancing inflammatory response of macrophages." (PMID 30510259, 2018). "Therefore, we hypothesized that Ninj1 would play an important role in the development of pulmonary fibrosis." (PMID 30510259, 2018).
pulmonary fibrosis (continued). "NINJ1 may contribute to the activation of macrophages by enhancing their interaction with epithelial cells, thereby facilitating neutrophil infiltration, inducing local inflammation, and promoting apoptosis in pulmonary fibrosis and liver ischemia-reperfusion injury." (PMID 39958360, 2025). "Thus, it was surprising that during colitis development, Ninj1 did not alter the migration capacity of macrophages, which is seen only in lung fibrosis." (PMID 31963519, 2020).